DNMT1 (DNA methyltransferase 1)
Diseases named in the same sentence as DNMT1 in open-access papers (continued):
Sharing a sentence is not in itself a finding about the gene and the disease.
DNMT1 also shares sentences with these, for which no sentence is quoted: multiple myeloma (11 papers); chronic myelomonocytic leukemia (9); neurodegenerative disease (7); coronary artery disease (6); psychosis (6); bipolar disorder (5); Immunodeficiency (5); amyloid (4); brain infarction (4); cardiac hypertrophy (4); dementia with Lewy bodies (4); mesothelioma (4); Myelodysplasia (4); neuropathies (4); pancreatic adenocarcinoma (4); benign prostatic hyperplasia (3); clear cell renal cell carcinoma (3); colorectal adenocarcinoma (3); colorectal adenoma (3); Hearing impairment (3); inflammation (3); invasive carcinoma (3); Myocardial fibrosis (3); scleroderma (3); testicular tumor (3); acute coronary syndrome (2); acute leukemia (2); acute myocardial infarction (2); anemia (2); bladder tumor (2).
A further 178 diseases each share a sentence with DNMT1 in 2 papers or fewer.